SDHAF4 (succinate dehydrogenase complex assembly factor 4)
Description:
Plays an essential role in the assembly of succinate dehydrogenase (SDH), an enzyme complex (also referred to as respiratory complex II) that is a component of both the tricarboxylic acid (TCA) cycle and the mitochondrial electron transport chain, and which couples the oxidation of succinate to fumarate with the reduction of ubiquinone (coenzyme Q) to ubiquinol. Binds to the flavoprotein subunit SDHA in its FAD-bound form, blocking the generation of excess reactive oxygen species (ROS) and facilitating its assembly with the iron-sulfur protein subunit SDHB into the SDH catalytic dimer (By similarity).
Synonyms: C6orf57; Sdh8
Tractability: Small molecule: a structure with a bound ligand is known.
Gene: Protein-coding gene on chromosome 6 (70,566,917 to 70,589,569, forward strand). Ensembl gene ENSG00000154079.
Subcellular location: Mitochondrion matrix
Subcellular location (Human Protein Atlas): Mitochondria; Nucleoplasm
Pathways (Reactome):
Metabolism: Maturation of TCA enzymes and regulation of TCA cycle
Gene Ontology:
Molecular function: protein binding; enzyme activator activity; protein folding chaperone
Biological process: cellular respiration; mitochondrial respiratory chain complex II assembly; tricarboxylic acid cycle; protein folding
Cellular component: mitochondrion; mitochondrial matrix
Genetic constraint (gnomAD): Loss-of-function variants: 9 observed, 8.12 expected, observed/expected ratio (o/e) 1.11, 90% interval 0.66 to 1.79. That is too few expected variants to judge how well the gene tolerates losing a copy. Missense variants: 102 observed, 77.51 expected, observed/expected ratio (o/e) 1.32, 90% interval 1.12 to 1.55. Synonymous variants: 49 observed, 31.46 expected, observed/expected ratio (o/e) 1.56, 90% interval 1.23 to 1.9.
Homologues: Orthologues: chimpanzee SDHAF4 (100% identical), dog SDHAF4 (84% identical), pig SDHAF4 (81% identical), guinea pig SDHAF4 (76% identical), mouse Sdhaf4 (68% identical), rat Sdhaf4 (66% identical), tropical clawed frog sdhaf4 (56% identical), zebrafish sdhaf4 (53% identical), Drosophila melanogaster Sirup (40% identical), Caenorhabditis elegans W02D3.12 (36% identical), Drosophila melanogaster CG15283 (34% identical).
Diseases named in the same sentence as SDHAF4 in open-access papers:
SDHAF4 is named in the same sentence as 15 diseases in open-access papers, as found by Europe PMC text mining. Sharing a sentence is not in itself a finding about the gene and the disease. The quoted sentences say what the papers report.
cardiomyopathy (1 paper, 2022). A disease of the heart muscle or myocardium proper. "More importantly, we predict that mutations in genes encoding complex II components, including SDHAF4, and/or dysregulation of their expression may be associated with cardiomyopathy in human patients." (PMID 35803927, 2022).
dilated cardiomyopathy (1 paper, 2022). Cardiomyopathy which is characterized by dilation and contractile dysfunction of the left and right ventricles. "Remarkably, decreased expression of SDHAF4 in the heart appears to be closely associated with human cardiac disorders, including DCM (dilated cardiomyopathy) and MCD (microvascular coronary disease)." (PMID 35803927, 2022).
heart failure (1 paper, 2022). Inability of the heart to pump blood at an adequate rate to meet tissue metabolic requirements. "Deficiency of SDHAF4 disrupted complex II assembly and promoted the degradation of SDH units, thereby progressively leading to metabolic dysfunction and excess mitophagy, which eventually resulted in DCM and heart failure." (PMID 35803927, 2022).
paraganglioma (1 paper, 2020). A benign or malignant neoplasm arising from paraganglia located along the sympathetic or parasympathetic nerves. "In 6 of them, we revealed the existence of pathogenic/likely pathogenic variants of genes encoding for components of the SDH complex (SDHB, SDHD, SDHAF3, and SDHAF4), confirming their high mutation frequency not only in paragangliomas and pheochromocytomas but also in VPGLs as distinct tumor types." (PMID 32948195, 2020).
metabolic disorders (1 paper, 2022). "Overall, the study indicates that the benefits of ADF may be from the suppression on mitochondrial complex II activity by decrease of SDHAF4 and that modulation of hepatic SDHAF4 level could be a possible approach for managing insulin sensitivity and related metabolic disorders." (PMID 35037426, 2022).
SDHAF4 also shares sentences with these, for which no sentence is quoted: adrenal pheochromocytoma (1 paper); carcinoma (1); gestational diabetes (1); heart diseases (1); infection (1); malnutrition (1); pheochromocytoma (1); schwannoma (1); Thyroid adenoma (1); tumor (1).